ENSG00000206898
Synonyms: LOC124900530
Gene: Small nucleolar RNA gene on chromosome 2 (10,296,047 to 10,296,180, reverse strand). Ensembl gene ENSG00000206898.
Gene Ontology:
Biological process: RNA processing
Cellular component: nucleolus
Homologues: Paralogues in human: SNORA51 (92% identical).